TRAV16 (T cell receptor alpha variable 16)
Description:
V region of the variable domain of T cell receptor (TR) alpha chain that participates in the antigen recognition. Alpha-beta T cell receptors are antigen specific receptors which are essential to the immune response and are present on the cell surface of T lymphocytes. Recognize peptide-major histocompatibility (MH) (pMH) complexes that are displayed by antigen presenting cells (APC), a prerequisite for efficient T cell adaptive immunity against pathogens. Binding of alpha-beta TR to pMH complex initiates TR-CD3 clustering on the cell surface and intracellular activation of LCK that phosphorylates the ITAM motifs of CD3G, CD3D, CD3E and CD247 enabling the recruitment of ZAP70. In turn ZAP70 phosphorylates LAT, which recruits numerous signaling molecules to form the LAT signalosome. The LAT signalosome propagates signal branching to three major signaling pathways, the calcium, the mitogen-activated protein kinase (MAPK) kinase and the nuclear factor NF-kappa-B (NF-kB) pathways, leading to the mobilization of transcription factors that are critical for gene expression and essential for T cell growth and differentiation. The T cell repertoire is generated in the thymus, by V-(D)-J rearrangement. This repertoire is then shaped by intrathymic selection events to generate a peripheral T cell pool of self-MH restricted, non-autoaggressive T cells. Post-thymic interaction of alpha-beta TR with the pMH complexes shapes TR structural and functional avidity.
Synonyms: TCRAV16S1; TCRAV9S1
Gene: T-cell receptor variable (V) gene on chromosome 14 (21,990,496 to 21,990,938, forward strand). Ensembl gene ENSG00000211796.
Subcellular location: Cell membrane
Gene Ontology:
Biological process: adaptive immune response
Cellular component: immunoglobulin complex; plasma membrane
Homologues: Orthologues: macaque TRAV16 (74% identical). Paralogues in human: TRAV8-4 (56% identical), TRAV8-2 (54% identical), TRAV8-6 (54% identical), TRAV3 (51% identical), TRAV8-1 (50% identical), TRAV8-3 (50% identical), TRAV8-7 (50% identical).
Diseases named in the same sentence as TRAV16 in open-access papers:
TRAV16 is named in the same sentence as 1 disease in open-access papers, as found by Europe PMC text mining. Sharing a sentence is not in itself a finding about the gene and the disease. The quoted sentences say what the papers report.
autoimmune disease (1 paper, 2024). A disorder resulting from loss of function or tissue destruction of an organ or multiple organs, arising from humoral or cellular immune responses of the individual to their own tissue constituents. "Genes related to these autoimmune diseases and Th17 cell differentiation, including CTLA4, IFN-ALPHA-8, IL12RB2, TRAV3, TRAV16, FOS, and VEGFA, were up-regulated in the E. coli group but down-regulated in the BL + E." (PMID 39707535, 2024).